PFKFB3 (6-phosphofructo-2-kinase/fructose-2,6-biphosphatase 3)
Diseases named in the same sentence as PFKFB3 in open-access papers (continued):
Sharing a sentence is not in itself a finding about the gene and the disease.
breast cancer (continued). "Here, we report that elevated Pfkfb3 expression correlates with the appearance of aggressive breast cancers and reduces relapse-free survival, as well as enhances BCSC self-renewal and metastatic outgrowth." (PMID 31413316, 2019). "As such, pharmacologic and genetic inactivation of autophagy dramatically upregulated Pfkfb3 expression in dormant breast cancer cells, thus enabling their outgrowth both in vitro and in vivo." (PMID 31413316, 2019). "Collectively, these findings suggest a role for Pfkfb3 regulating metastatic relapse and recurrence by disseminated breast cancer cells." (PMID 31413316, 2019). "More importantly, our findings implicate Pfkfb3 as an autophagy substrate that interacts physically with the cargo adaptor protein, p62/SQSTM1, thereby modulating the expression levels of Pfkfb3 in disseminated breast cancer cells." (PMID 31413316, 2019). "Unfortunately, we were unable to monitor the impact of chronic CQ administration (5–7 days) on Pfkfb3 expression in D2.OR organoids due to its cytotoxic activities, which were surprisingly similar across several human and murine breast cancer cell lines." (PMID 31413316, 2019). "Since PFKFB3 gene is significantly and positively correlated with compressive stress markers in all the subtypes of breast cancer, its correlation with EMT- or angiogenesis-related genes was further analyzed." (PMID 31428701, 2019). "Collectively, these findings indicate that aberrant Pfkfb3 expression occurs frequently in metastatically proficient and aggressive breast cancers, leading to reduced RFS in breast cancer patients." (PMID 31413316, 2019). "Breast cancer patients with high PFKFB3 expression showed a significant poorer prognosis than those with low PFKFB3 expression." (PMID 31428701, 2019). "It has been found that miR-26b and miR-206 interact with the 3′UTR of the PFKFB3 mRNA, decreasing glycolysis in osteosarcoma and breast cancer cells, respectively." (PMID 30234009, 2018). "PFKFB3 is a direct target of E2 action; in ER-responsive breast cancer cells (MCF-7), E2 promotes PFKFB3 mRNA transcription and up-regulates PFKFB3 protein expression through ERα via direct binding to PFKFB3 promoter." (PMID 29543707, 2018). "Recently, Swedish researchers found that PFKFB3 mRNA levels of breast CSCs and breast cancer cells in vitro were significantly higher than induced pluripotent stem (iPS) cells and human primary fibroblasts." (PMID 28977989, 2017). "A relatively high expression of PFKFB3 was also reported in asynchronous breast cancer cell lines and HeLa cells, which shows that cell cycle synchronization is not always required for the detection of PFKFB3." (PMID 26337471, 2015). "Initial validation using PFKFB3 siRNA showed ∼30% of silencing in all breast cancer cell lines analyzed." (PMID 26337471, 2015). "Significant upregulation of the PFKFB3 mRNA level was observed in all three breast cancer cell line-derived CSC compared with the parent breast cancer cells." (PMID 26337471, 2015). "Expression of PFKFB3 in SKBR3 breast cancer cells decreased after 24 h incubation with 10 mM 2-deoxy-D-glucose (2-DG)." (PMID 26337471, 2015). "Additionally, paclitaxel resistance in breast cancer is conferred by PFKFB3 stability both in vitro and in vivo." (PMID 40295451, 2025). "Furthermore, PFKFB3 can regulate the cell cycle progression of breast cancer cells by downregulating p27 through AKT phosphorylation, which affects ERα stability and modulates sensitivity to endocrine therapy." (PMID 40303296, 2025). "Moreover, proviral insertion in murine lymphomas 2 is a proto‐oncogene that mediates PFKFB3 phosphorylation, which can confer paclitaxel resistance in breast cancer." (PMID 40956032, 2025). "Thus, PFKFB3 is a potential target for radiosensitization treatment, which is needed in the treatment of several cancer forms including breast cancer." (PMID 40022029, 2025).
breast cancer (continued). "Furthermore, in multiple advanced drug-resistant breast cancer models, the integrated application of PFKFB3 inhibitors and ER+ targeted therapies demonstrate high efficacy in overcoming chemoresistance, including TAM and PTX." (PMID 40264038, 2025). "In conclusion, we observed varying PFKFB3 RNA expression in different breast cancer subtypes." (PMID 40022029, 2025). "To bolster the clinical relevance of our experiments, we examined the effect of Pfkfb3 deletion on established mammary tumors to mimic conditions wherein therapeutic intervention by manipulation of PFKFB3 activity might be anticipated." (PMID 39001392, 2024). "Whereas Pfkfb3 was deleted in Erbb2 mice after mammary tumors were well established and the period of observation was relatively short due to the rapid growth of the control tumors, Pfkfb3 was deleted in K-rasLA1 mice at 6 weeks of life and the mice were observed for a prolonged time period." (PMID 39001392, 2024). "Inhibition of AMPK or PFKFB3 can sensitize breast cancer cells to microtubule poisons." (PMID 37444501, 2023). "PFKFB3 promoted the proliferation and migration of breast cancer in a hyperglycemic environment and might be regulated by miR-26." (PMID 36973739, 2023). "Dormant breast cancer cells show low levels of 6-phosphofructo-2-kinase/fructose-2,6-biphosphatase 3 (PFKFB3) and high autophagy activity, whereas metastatic breast cancer cells show high levels of PFKFB3 and low levels of autophagy." (PMID 36831154, 2023). "In conclusion, PFKFB3 could be overexpressed by hyperglycemia and might be a potential therapeutic target for breast cancer complicated with diabetes." (PMID 36973739, 2023). "Briefly, PFKFB3 knockdown could remarkably suppress the proliferation and migration of breast cancer in a hyperglycemic environment." (PMID 36973739, 2023). "PFKFB3 is overexpressed in breast cancer, colon cancer, NSCLC, and HCC." (PMID 37919747, 2023). "PFKFB3 (6-phosphofructose-2-kinase/fructose-2, 6-bisphosphatase 3) is a key regulatory factor of the glycolysis process in diabetes mellitus, as well as a promoter of breast cancer." (PMID 36973739, 2023). "Overexpression of tRiMetF31 profoundly suppressed migration and angiogenesis of breast cancer cells by silencing PFKFB3, which might represent a target molecule for therapeutic intervention." (PMID 37864150, 2023). "Besides, to investigate the role of PFKFB3 in the biological behaviors of breast cancer such as proliferation and migration in hyperglycemic environment, cell functional experiments were carried out." (PMID 36973739, 2023). "In addition, PFKFB3 stimulated epithelial-mesenchymal transition of breast cancer in a hyperglycemic environment." (PMID 36973739, 2023). "In general, we deduced that hyperglycemia might upregulate PFKFB3 expression by inhibiting miR-26 to promote the malignant phenotype of breast cancer." (PMID 36973739, 2023). "It is known that PFKFB3 promotes the proliferation, invasion, and migration of breast cancer cells." (PMID 37919747, 2023). "PFKFB3 has been found to promote breast cancer cell survival under mitotic arrest conditions." (PMID 37444501, 2023). "Based on the results above, we could deduce that PFKFB3 overexpression by hyperglycemia might be by the way of miR-26 downregulation in breast cancer." (PMID 36973739, 2023). "PFKFB3 expression was significantly upregulated in breast cancer tissues." (PMID 36973739, 2023). "Interestingly, La Belle Flynn and collaborators determined a key role for the glycolytic enzyme 6-phosphofructo-2-kinase/fructose-2,6-biphosphatase 3 (Pfkfb3) in driving the balance between dormancy and awake in breast cancer cells." (PMID 35158815, 2022).
breast cancer (continued). "Circ_0102273 is mentioned as a regulator of PFKFB3 and is upregulated in breast cancer." (PMID 36230935, 2022). "PFKFB3 may function as an oncogene in tumorigenesis, since the overexpression of PFKFB3 has been demonstrated in numerous malignancies, including breast cancer." (PMID 35961977, 2022). "Interestingly, as a predicted target of tRiMetF31, PFKFB3 was upregulated in all breast cancer cell lines and overexpressed in three out of the seven brain cancer cell lines tested." (PMID 35961977, 2022). "PFKFB3 was overexpressed in all breast cancer cell lines and in 42.9% of brain cancer cell lines (n = 7) tested, which may be attributed to the downregulation of tRiMet31 in these cell lines." (PMID 35961977, 2022). "Also, a high expression of PFKFB3 is a prognostic factor of poor prognosis in human HER2+ breast cancer and it correlates with TNM in lung adenocarcinoma." (PMID 35626081, 2022). "Thus, we examined the contributing role of tRiMetF31-triggered downregulation of PFKFB3 in breast cancer migration and angiogenesis using HCC1806 and MCF7 cell lines." (PMID 35961977, 2022). "Interestingly, the meta-analysis showed an overexpression of PFKFB3 in breast cancer tissues, which was significantly correlated with tumor size and metastasis." (PMID 35961977, 2022). "Inhibition of AMPK or PFKFB3 led to cell death of breast cancer cells." (PMID 33671514, 2021). "We demonstrates that PIM2 mediates PFKFB3 phosphorylation thus regulates glycolysis and paclitaxel resistance to promote tumor progression in breast cancer, and provides preclinical evidence for targeting PFKFB3 as a new strategy in breast cancer treatment to battle paclitaxel resistance." (PMID 33931981, 2021). "Furthermore, we observed Pfkfb3 staining intensity to be varied both within and amongst individual breast cancer subtypes, thereby demonstrating that Pfkfb3 expression is frequently upregulated across the spectrum clinical breast cancer subtypes." (PMID 31413316, 2019). "Pfkfb3 expression and autophagy exhibited an inverse relationship, such that dormant breast cancer cells displayed a Pfkfb3LowAutophagyHigh phenotype that gave way to a Pfkfb3HighAutophagyLow phenotype in metastatic breast cancer cells." (PMID 31413316, 2019). "Thus, measures capable of inactivating autophagy appear to be competent in promoting Pfkfb3 expression and the reactivation of proliferative programs in dormant breast cancer cells." (PMID 31413316, 2019). "In contrast to our finding, PFKFB3 was reported to be constitutively overexpressed in different cancer cell lines, several human leukemias, and multiple solid tumors such as ovarian cancer, thyroid cancer, breast cancer, gastric tumors, and pancreatic cancer." (PMID 31847435, 2019). "Similar elevations in Pfkfb3 mRNA and protein expression were observed in a variety of established human breast cancer cell lines relative to HMECs; however, it should be noted that the correlation between Pfkfb3 mRNA and protein expression varies slightly within human breast cancer cell lines." (PMID 31413316, 2019). "The SKBR 3 breast cancer cell line was selected to conduct further analysis upon PFKFB3 silencing." (PMID 26337471, 2015). "In contrast to mRNA expression data, elevated expression of PFKFB3 was detected only in SKBR 3-derived CSCs by Western blots, suggesting increased degradation or differential regulation of PFKFB3 gene expression in CSCs sorted from MDAMB 468 cells or BT 474 breast cancer cells." (PMID 26337471, 2015). "Similarly, the sonic Hedgehog pathway can activate PFKFB3 in breast cancer cells." (PMID 37626891, 2023). "Indeed, autophagy-related protein silencing in dormant breast cancer cells stabilize PFKFB3." (PMID 36831154, 2023). "In our study, PFKFB3 expression was firstly confirmed to be enhanced by mediums with high glucose concentration and the knockdown of PFKFB3 could inhibit the malignant phenotype of breast cancer." (PMID 36973739, 2023).
breast cancer (continued). "Besides, hyperglycemia might enhance PFKFB3 expression by miR-26 down-regulation to promote the proliferation and migration of breast cancer via activating RAS/MAPK signaling pathway." (PMID 36973739, 2023). "PFKFB3 was overexpressed in tumor samples and could promote breast cancer xenograft growth." (PMID 35242214, 2022). "Therefore, we investigated whether PFKFB3 expression is related with a poor prognosis of breast cancer patients." (PMID 31428701, 2019). "Finally, BCSCs represent the tumor-initiating component of dormant breast cancer micrometastases, and as such, we hypothesized that Pfkfb3 could play an important role in mediating the stemness of these specialized breast cancer cells." (PMID 31413316, 2019). "Additionally, PFKFB3 inhibitors triggered cell cycle arrest of breast cancer cells in G2 phase, suggesting that inhibition of PFKFB3 could prevent cancer cells from proliferation." (PMID 28977989, 2017). "Interestingly, P4 has been reported to induce PFKFB3 in human breast cancer cells, suggesting that PFKFB3 may mediate P4 mitogenic effects both in normal and abnormal physiologic contexts." (PMID 24204309, 2013). "Previous studies have established its role in post-translational modification of metabolic enzymes including PFKFB3, PKM2, and PHGDH, which collectively promote de novo fatty acid biosynthesis in breast cancer models." (PMID 41501793, 2026). "In a human epidermal growth factor receptor 2 (HER2 positive) breast cancer mouse model, inhibition of PFKFB3 reduced glucose uptake as well as tumor growth, making it a promising treatment target in HER2 positive breast cancer." (PMID 40022029, 2025). "In PTX-resistant breast cancer, proline, glutamic acid, leucine-rich protein 1 (PELP1) directly interacts with PFKFB3, leading to breast cancer cells exhibiting high glycolytic characteristics." (PMID 40264038, 2025). "Our results indicated that the resultant decrease in PFKFB3 expression and activity significantly reduced F26BP and growth in established HER2/Erbb2+ mammary tumors." (PMID 39001392, 2024). "We monitored the mammary tumor burden in the groups by caliper measurements and found that TAM-induced Pfkfb3 deletion led to a marked suppression of tumor growth." (PMID 39001392, 2024). "PFKFB3 is a hub for coordinating cell cycle and glucose metabolism by binding CDK4 and inhibiting the degradation of CDK4 in breast cancer." (PMID 37253634, 2023). "The combination of PFKFB3 and PIM2 has been reported to increase the glucose level in breast cancer cells (glucose detection kit, Sigma, GAGO20), so what role does PFKFB3 play in breast cancer patients with diabetes?" (PMID 36973739, 2023). "In other words, PFKFB3 knockdown inhibited the EMT and RAS/MAPK pathway of breast cancer in a hyperglycemic environment." (PMID 36973739, 2023). "Western blot was adopted to analyze the protein level of PFKFB3, epithelial–mesenchymal transition (EMT)-related protein and extracellular regulated protein kinases (ERK) in breast cancer cells." (PMID 36973739, 2023). "PFK158, the PFKFB3 inhibitor, has been approved by the FDA in clinical trials with pancreatic cancers and breast cancers, as well as many other cancers." (PMID 36016583, 2022). "Breast cancer shows an increased expression of glycolysis-related enzymes, namely, HKII, 6-phosphofructo-2-kinase/fructose-2, 6-biphosphatase 3 (PFKFB3), and pyruvate kinase M2 (PKM2)." (PMID 34552932, 2021). "We next analyzed the expression profile of PFKFB3 and PFK1 proteins in FACS-sorted breast cancer cell line-derived CSC, iPS cells, and human primary fibroblasts (the material for production of iPS cells) by Western blot and qRT-PCR." (PMID 26337471, 2015). "In regards of PFKFB3 not being a prognostic marker in breast cancer, previous studies have shown the opposite." (PMID 40022029, 2025).
breast cancer (continued). "The hypoxia pathway was enriched in all three groups compared to the lowest one but without a stepwise correlation, indicating that hypoxia is not an important source for PFKFB3 increase in this breast cancer subset." (PMID 40022029, 2025). "In the light of these results, PFKFB3 does not appear to be useful prognostic marker in early-stage breast cancer." (PMID 40022029, 2025). "The SweBCG91RT trial, in which breast cancer patients were randomized to postoperative radiotherapy or not, was used to investigate PFKFB3 as a clinical marker of sensitivity to adjuvant radiotherapy." (PMID 40022029, 2025). "Their findings revealed that Pfkfb3 is expressed in metastatic breast cancer cells but absent in dormant cells." (PMID 38795254, 2024). "The inhibition of PFKFB3 suppresses glucose metabolism and the growth of HER2+ breast cancer." (PMID 39408832, 2024). "In breast cancer, the lncRNA BCAR4 was identified as a downstream target of YAP that controls cancer development, by reprogramming glucose metabolism through the transcription of two glycolysis activators, Hexokinase 2 (HK2) and PFKFB3." (PMID 37689702, 2023). "Briefly, the results indicated that PFKFB3 expression level might be correlated with the activation of RAS/MAPK and EMT pathways in breast cancer." (PMID 36973739, 2023). "The elevated expression of PFKFB3 was reported in numerous human malignancies, including HER2+ breast cancer, head and neck squamous cell carcinoma, hepatocellular carcinoma, colon carcinoma, neuroblastoma, and pancreatic cancer, correlated with poor prognosis." (PMID 35454815, 2022). "3PO, a PFKFB3 inhibitor, reduces the size of tumors in HER2+ mice with breast cancer." (PMID 36059650, 2022). "Moreover, overexpression of PFKFB3 can increase the expression of VEGF-A, thereby promoting angiogenesis and facilitating metastasis in breast cancer." (PMID 32631382, 2020). "Here, the authors show that Pfkfb3, a glycolytic gene, is expressed in metastatic breast cancer cells but not in dormant cells that demonstrate features of autophagy." (PMID 31413316, 2019). "Among three compression-upregulated metabolic genes, the protein expression of HK2 and PFKFB3 genes were detected in breast cancer stromal tissues but not in normal tissue." (PMID 31428701, 2019). "Among the compression-upregulated metabolic genes, the expression of ENO2 gene was significantly and positively correlated with COL3A1 and HAS1 genes, whereas PFKFB3 genes were significantly and positively correlated with that of COL1A1, HAS2, and HAS3 genes in breast cancer patient tissues." (PMID 31428701, 2019). "Selective targeting of PFKFB3 by siRNA or 3-PO resulted in a significant decrease of extracellular lactate in breast cancer cells and a moderate decrease in iPS cells, but not in fibroblasts." (PMID 28977989, 2017). "Furthermore, PFKFB3 protein is highly phosphorylated at Ser461, the consensus site for AMPK, PKA and PKC, in colon and breast carcinoma compared to epithelial cells from normal tissue, suggesting enhanced PFK-2 activity in cancer." (PMID 24280138, 2013). "However, the relationship between expression of PFKFB3 in non-treated breast cancer cells and radiotherapy has not been studied." (PMID 40022029, 2025). "In addition, PFKFB3 can also be phosphorylated by lncRNA YIYA, increasing the conversion of fructuce-6-phosphate to fructuce-2, 6-Bisphosphate, and promoting the reprogramming and growth of glucose metabolism in breast cancer." (PMID 34560889, 2021). "Finally, we investigated the autophagic state of these same human breast cancer tissues by IHC staining for the autophagy mediators p62/SQSTM1, LC3, and Atg3, whose expression was compared with that of Pfkfb3." (PMID 31413316, 2019). "In contrast to previous reports, we did not observe cell cycle-dependent changes in PFKFB3 expression in synchronized breast cancer cells, a discrepancy which could result from possible overexpression of PFKFB3 in the cell lines analyzed." (PMID 26337471, 2015).